SIRT1 (sirtuin 1)
Diseases named in the same sentence as SIRT1 in open-access papers (continued):
Sharing a sentence is not in itself a finding about the gene and the disease.
tumor (continued). "Besides, SIRT1, 2, and 4 showed increased expression levels in tumor tissues, which probably accounted for widespread deacetylation of the non-histone proteins, and may serve as diagnostic predictors of HCC." (PMID 33093847, 2020). "Also, multiple foci of SIRT1 expression are dispersed throughout the tumor parenchyma (bottom row)." (PMID 32118205, 2020). "Thus, our results further support a tumor-suppressive role of SIRT1 in RCC." (PMID 32340156, 2020). "However, it was later observed that the reduced activity of SIRT1 compromised genetic instability, and, thus, it was suggested that it may function as a tumor suppressor." (PMID 32486270, 2020). "In contrast, in certain situations, SIRT1 may act as tumor suppressor." (PMID 31847543, 2020). "In several types of cancer, SIRT1 is elevated and may serve as a tumor promoter." (PMID 31847543, 2020). "However, numerous studies reported the role of SIRT1 as a tumor suppressor." (PMID 31598701, 2019). "However, either directly targeting SIRT1, combining conventional chemotherapy with SIRT1 inhibitors, or upregulating tumor-suppressive miRNAs may improve therapeutic efficacy and patient outcomes." (PMID 31608282, 2019). "Immunoblot analysis showed a significant increase of K382 acetylation in the tumours obtained from patients treated with ketorolac as compared to controls (treated with opiates), indicating that SIRT1 inhibition could be promoted by a single NSAID treatment during surgery." (PMID 30739913, 2019). "Cytoplasmic SIRT1 might inhibit the migration and invasion of tumor cells by impeding the EMT." (PMID 31317367, 2019). "The role of SIRT1 as a tumor suppressor or oncogene may depend on its subcellular localization." (PMID 31317367, 2019). "However, a context dependent tumour suppressive role for SIRT1 has previously been proposed." (PMID 31727006, 2019). "However, the tumor microenvironment is highly dynamic and SIRT1 expression may be heterogeneous in different cellular subpopulations at different time points." (PMID 31608282, 2019). "They postulated that SIRT1 suppression leads to E-cadherin degradation from the cell surface, thereby releasing β-catenin from the cadherin junctions to the nucleus, which is the characteristic of mesenchymal cells, thus asserting SIRT1 tumor-suppressive properties in the EMT process of BC." (PMID 30380732, 2018). "Therefore, when using Hsp90 inhibitors in tumor chemotherapy one might need to consider the potential impact of SIRT1 inhibition especially in tumors where SIRT1 suppresses malignancy." (PMID 30463299, 2018). "Hence, considering that solid tumors are composed by a clones plethora subject to selective pressure, it is tempting to propose the monitoring of SIRT1 expression/activity as source of information on the efficiency of treatments related to tumor evolution at the cellular scale." (PMID 30319540, 2018). "However, other studies also suggest that SIRT1 may also have tumor-suppressive function in some mouse model." (PMID 29435152, 2018). "Next, we wondered whether SIRT1 inhibits tumor metastasis in vivo." (PMID 30250020, 2018). "Additionally, SIRT1 overexpression attenuated the suppressive effect of miR-30a on tumor growth, suggesting that miR-30a might inhibit tumor growth by silencing SIRT1." (PMID 29435152, 2018). "Furthermore, SIRT1 facilitates tumor maintenance, and targeting SIRT1 may reduce the tumor burden during androgen deprivation." (PMID 29416748, 2018). "Notably, both suboptimal and excess levels of SIRT1 have a tumor suppressive impact in rodents." (PMID 28703423, 2017). "However, the role of SIRT1 in the progression of spontaneous neoplasms remains elusive." (PMID 28903430, 2017).
tumor (continued). "However, the role of SIRT1 in various human tissues and tumor models are still controversial." (PMID 28600541, 2017). "Moreover, immunoprecipitation and Western blotting results clearly showed functional and physical interactions between NF-κB and Sirt1, highlighting that this interaction may play an important role in regulating resveratrol’s anti-tumor effects in CRC." (PMID 26959057, 2016). "Furthermore, MMP3 is SIRT1-dependently secreted from fibroblasts and facilitates tumor growth." (PMID 26992208, 2016). "Furthermore, we demonstrated that MSCs-Sirt1 could induce apoptosis and inhibit proliferation to suppress 4T1 tumor growth in vivo." (PMID 27782173, 2016). "In Bioluminescence Imaging Analysis, the fluorescence photon flux (which has a linear relationship with the number of tumor cells) was significantly reduced in SIRT1-depleted cells compared to control cells, but this inhibitory effect could be reversed by the overexpression of PGC-1α (Figure 8A2)." (PMID 27081083, 2016). "Interestingly, some studies have claimed that SIRT1 inhibits tumour progression and invasion." (PMID 27793039, 2016). "Furthermore, Sirt1 may act as a tumor suppressor through improving genetic stability, as shown in in vivo normal tissue cells, and in addition to that, Sirt1 regulates other signaling mechanisms." (PMID 26959057, 2016). "Considering SIRT1 activity was essential for maintaining growth and self-renewal of liver CSCs, so we focused on analyzing whether SIRT1 was involved in promoting liver CSCs self-renewal and tumor development mediated by MEK1." (PMID 26967560, 2016). "If so, the SIRT1-specific effect on tumor growth could be masked by this bystander effect." (PMID 26992208, 2016). "Intriguingly, some other studies have shown that SIRT1 may act as a tumor suppressor." (PMID 27708228, 2016). "Many mechanisms may be involved in the control of tumor progression by SIRT1/2." (PMID 25915617, 2015). "However, the role of SIRT1 in tumorigenesis remains controversial, and may depend on the tumor type." (PMID 25424420, 2014). "However, it remains controversial whether SIRT1 acts as a tumor promoter or suppressor due to the temporal and special distribution of different SIRT1 upstream and downstream targets and factors in different tissue contexts." (PMID 25522783, 2014). "However, convincing evidence has also demonstrated the tumor suppressor function of SIRT1." (PMID 25922660, 2014). "Thus, the functions of SIRT1 in stimulating cell growth and angiogenesis, and blocking senescence and apoptosis indicate that SIRT1 may play a critical function in tumor initiation, progression, and drug resistance." (PMID 25486244, 2014). "However, an opposite role for SIRT-1 as a tumor suppressor in HCC has also been proposed." (PMID 25533006, 2014). "Thus, SIRT1 has a dual role in tumorigenesis whose manifestation may depend on the specific cell, tumor type, stage, or differentiation level." (PMID 23460888, 2013). "Paradoxically, a growing body of evidence suggests that SIRT1 may suppress tumor development." (PMID 23799088, 2013). "Intriguingly, APC+/min mice exhibiting whole-body SIRT1 deficiency developed a similar number of intestinal polyps as the APC+/min controls, but demonstrated significantly decreased average polyp size, indicating that SIRT1 could actually promote tumor growth." (PMID 23799088, 2013). "However, other publications have indicated that SIRT1 has tumor-suppressive functions in vivo." (PMID 24223900, 2013). "Despite the results of these animal studies, mutations in SIRT1 gene have never been documented in human tumors, indicating that SIRT1 may not behave as a typical tumor suppressor." (PMID 23799088, 2013). "However, an additional potential mechanistic explanation for SIRT1 tumor promoting activity may involve the activation of oncogenes in addition to c-Myc." (PMID 23024800, 2012).
tumor (continued). "On the premise that SIRT1 acts as a tumor suppressor, SIRT1 could be downregulated in many tumors." (PMID 23050959, 2012). "However, SIRT1 also exerts opposite effects, acting as a tumor promoter." (PMID 23050959, 2012). "SIRT1 overexpression could provide tumor cells a survival advantage." (PMID 22479397, 2012). "However, further investigation is required to fully clarify whether subcellular localization of SIRT1 is indeed a fate-determinant of its oncogenic versus tumor-suppressing functions." (PMID 23050959, 2012). "We then examined whether suppression of SIRT1 activity could partly block tumor initiation in vivo." (PMID 21698133, 2011). "Sirt1 levels are increased in a number of tumor types although only few mechanisms of Sirt1 regulation have been described highlighting the requirement for further deciphering the genetic alterations that have occurred during tumorigenesis that may affect Sirt1." (PMID 19828042, 2009). "NAD-dependent protein deacetylase sirtuin-1 (SIRT1) is an NAD+-dependent deacetylase whose enzymatic activity can be augmented by SUMOylation, and it plays dual roles in tumour suppression and oncogenesis." (PMID 41362746, 2026). "Inhibition of SIRT1 using EX527 reduces PD-L1 nuclear translocation, suppresses tumor growth, and enhances the efficacy of anti-PD-L1 immunotherapy." (PMID 41471349, 2025). "Single‐cell RNA sequencing data further confirmed heterogeneous expression of SIRT1 across key cell populations within MGM, brain–tumor interface, and dura mater tissues." (PMID 41208649, 2025). "Benserazide, an inhibitor of CBS, in combination with paclitaxel, decreased SIRT1 sulfhydration and hypoxia-inducible factor 1-alpha/vascular endothelial growth factor (HIF-1α/VEGF) expression in tumor models." (PMID 41465271, 2025). "However, the role of SIRT1 in tumor development remains unclear." (PMID 40136510, 2025). "CANA reduces oxidative stress and improves energy metabolism by activating sirtuin 1 (SIRT1), a nicotinamide adenine dinucleotide (NAD)+-dependent class III histone deacetylase, in some non-tumor tissues." (PMID 39940750, 2025). "For example, gallotannin induces senescence and impairs autophagy by regulating the SIRT1/AMPK axis, decreasing SIRT1 and mTOR expression while enhancing AMPK phosphorylation, leading to tumor growth inhibition." (PMID 40052151, 2025). "Conversely, studies have indicated that SIRT1 overexpression serves as a positive prognostic factor for CRC, indicate its tumor inhibitory functions." (PMID 40229278, 2025). "Mechanistically, USP22 stabilizes SIRT1 via deubiquitination, subsequently activating the TAK1/Akt-ERK signaling axis to drive tumor progression." (PMID 41301681, 2025). "The overexpression of Sirt1 reduces the protein level of FOXO1, resulting in the inhibition of androgen production in U87 cells, consequently suppressing tumor cell proliferation and invasion." (PMID 40075208, 2025). "In our study, high Sirt1 expression correlated with improved survival among GBM patients, suggesting its role as a tumor suppressor gene." (PMID 40075208, 2025).
tumor (continued). "Specifically, SIRT1 transferred via CAA-EVs promotes an increase in M2 macrophages, which are known for their immunosuppressive and tumor-promoting roles." (PMID 40330466, 2025). "While SIRT1, SIRT2, and SIRT6 can assume opposite functions in relation to the tumor context, SIRT3, SIRT4, and SIRT7 tend to function more in favor of tumors." (PMID 41425553, 2025). "Given its high expression in certain tumor tissues and its inhibition of several tumor suppressor genes like FOXO1, p73, and WRN, SIRT1 is believed to promote tumorigenesis." (PMID 39944690, 2025). "Conversely, SIRT1 promotes the binding of AKT and PDK1 to PIP3 by deacetylating them, thereby activating AKT signalling and tumour growth." (PMID 39778006, 2025). "Recent investigations have progressively identified members of the sirtuin family, notably SIRT1 and SIRT2, as key regulators of multiple adaptive strategies used by tumor cells to avoid chemotherapy-induced lethal effects." (PMID 41425553, 2025). "SIRT1 plays a complex role in TNBC, acting as both a promoter and suppressor of tumor progression depending on the context." (PMID 41300302, 2025). "When SIRT1 reduces acetylation of H3K9 to inhibit the expression of an antiapoptotic protein, survivin, it can inhibit tumor formation and growth." (PMID 40283998, 2025). "Further studies have identified molecules related to tumor MDR at the cellular level, such as downregulated miR-34a-5p and upregulated Activating Transcription Factor 4/(ATF4), both of which target SIRT1." (PMID 40567502, 2025). "SIRT1 overexpression decreased intracranial androgen and suppressed GBM growth, implicating a tumor-suppressive activity by endocrine regulation." (PMID 41425553, 2025). "Similar to SIRT1, SIRT2 is also shown to have both tumorigenic and tumor-suppressive roles, but most of the latest evidence corroborates the former role." (PMID 41471349, 2025). "Overexpression of Sirt1 reduces FOXO1 acetylation, lowers androgen synthesis enzyme levels, and effectively decreases brain androgen levels, thereby delaying tumor progression." (PMID 40075208, 2025). "Activated SIRT1 leads to the deacetylation of hMOF, reducing H4K16 acetylation, which promotes a tumor-supporting phenotype in the microglia." (PMID 40710366, 2025). "GMDS-AS1 stabilizes SIRT1 mRNA by recruiting TAF15, leading to p65 deacetylation and reduced MMP-9 expression, acting as a tumor suppressor in LUAD." (PMID 40684184, 2025). "This indicates that when SIRT1 activity is low, PMN-MDSCs are less capable of maintaining their suppressive state, thereby allowing T cells to be more effective against the tumor." (PMID 41425553, 2025). "To evaluate how the activation of the NAD+ salvage pathway affects tumor growth, we evaluated the cell viability of the NAMPT inhibitor FK866 in combination with CANA to suppress the NAMPT-NAD+-SIRT1 pathway." (PMID 39940750, 2025). "Both Sirt1 overexpression and finasteride effectively reduced peripheral blood DHT levels in tumor-bearing mice." (PMID 40075208, 2025). "This places SIRT1 as a downstream effector of vitamin D/VDR signaling, thus connecting dietary and genetic modulation of tumor behavior." (PMID 41425553, 2025).
tumor (continued). "We demonstrated that SIRT1 inhibition by EX527 reduced PD‐L1 nuclear localization, enhanced the antitumor immune response, and significantly diminished tumor growth in vivo." (PMID 39988985, 2025). "Other studies have reported that the combination of a SIRT1 inhibitor with anti-CRC drugs such as 5-FU, SN-38, or oxaliplatin can promote cell apoptosis and enhance the anti-tumor effect." (PMID 40567502, 2025). "A previous paper reported that inhibiting SIRT1, an NAD+-dependent enzyme, induces cyclin D1 downregulation and suppresses tumor growth in HCC cells." (PMID 39940750, 2025). "SIRT1 upregulation in drug-resistant cells promotes autophagy and EMT; SIRT1 inhibition suppresses autophagy, EMT, and tumor growth." (PMID 41425553, 2025). "EA treatment decreased tumor numbers, inflammation, and DAI scores, while increasing body weight and SIRT1 expression." (PMID 39403142, 2024). "Other genes were modulated in a different way in all three SCCs (NMNAT1, NMNAT2, NADSYN1, SIRT3, and CD38) or in two tumor types (NNMT, NMNAT3, ENPP2, PNP, and SIRT1)." (PMID 38254798, 2024). "RT-qPCR and Western blot analyses revealed that, compared to the sh-NC group, the sh-SIRT1 group had significantly lower expressions of BNIP3, PINK1, and PRKN and their corresponding proteins in the tumor tissues." (PMID 39266959, 2024). "Recent studies have confirmed that SIRT1 can promote angiogenesis via the deacetylation of HIF-1α and the regulation of VEGF expression, providing support for tumor growth and metastasis." (PMID 39845948, 2024). "Its ability to modulate autophagy and mitigate mitochondrial ROS generation, particularly via the SIRT1- and SIRT3-mediated pathways, highlights its potential utility in disrupting tumor growth." (PMID 39682281, 2024). "SIRT1 influences apoptosis and chemoresistance through hypoxia, enhancing glycolytic metabolism and HIF-1α signaling, which sustain tumor survival against drugs like gemcitabine." (PMID 39682281, 2024). "Interestingly, while SIRT1 inhibition under androgen deprivation induces cellular senescence, enhancing the efficacy of AR blockade and radiation therapy, its silencing in hormone-responsive LNCaP cells mimics AR inhibition, resulting in smaller tumor formation." (PMID 39796040, 2024). "Among the sirtuins, SIRT1, SIRT3, SIRT4, and SIRT6 have been identified as significant targets for anti-tumor treatments; SIRT4 has been proposed as a tumor-suppressor protein, reducing glutamine entry into mitochondria in response to DNA damage." (PMID 39195514, 2024). "To further explore the mechanism by which SIRT1 induces hormone resistance, we examined the expression of SIRT1, FOXO3, LC3B, and p62 proteins in EC tumor tissues from mice using immunohistochemistry." (PMID 39266959, 2024). "However, SIRT1 expression is often reduced in other human tumors (such as glioblastoma, bladder carcinoma, and prostate carcinoma, among others) indicating it may, also, function as a tumor suppressor." (PMID 39766219, 2024). "Studies have indicated that Sirtuin 1 (SIRT1) is an attractive therapeutic target for reversing EMT and tumor metastasis." (PMID 39335456, 2024). "In this study, we found that MA, a pentacyclic triterpenoid, not only attenuated DOX-induced cardiotoxic effects through the SIRT1-activated signaling pathway but also enhanced the anticancer effects of DOX, providing a dual beneficial effect on tumor therapy." (PMID 39494326, 2024).